DCX (doublecortin)
Diseases named in the same sentence as DCX in open-access papers (continued):
Sharing a sentence is not in itself a finding about the gene and the disease.
Stroke (continued). "Following stroke, endogenous stem cells are activated in the SVZ and, after asymmetric cell division, DCX+ neuroblasts are generated and migrate into the striatal or cortical stroke area away from the rostral migratory stream." (PMID 34447293, 2021). "In the present study, to observe the neurogenesis in ischemic cortex after stroke regulated by IL-17 and As-IV, NPC markers-Nestin, GFAP and Sox2 and immature neuron marker-DCX, and mature neuron marker-NeuN protein expression was chose." (PMID 32818074, 2020). "We observed significantly (p = 0.064) decreased level of DCX expression in the right (ischemic) cerebral hemisphere of MCAO + vehicle rats at 24 h post MCAO, which reflected the adverse effect of stroke on NPCs population." (PMID 32728189, 2020). "In this study, As IV promoted the expression of the DCX, BrdU, and Sox2 proteins in the subgranular zone (SGZ) after stroke in vivo." (PMID 32317974, 2020). "In this study, knocking out IL-17 significantly promoted the expression of BrdU, DCX, Nestin, and Sox2 in the SGZ after stroke in vivo, which was consistent with the results by giving As IV above." (PMID 32317974, 2020). "We observed significantly decreased expression of DCX and HuC/HuD in MCAO + vehicle rats, which suggested decreased NPCs population as well as their differentiation potential after stroke." (PMID 32728189, 2020). "After 7 days of stroke, SOX2-positive cells and BrdU/DCX-double positive proliferative NPCs were significantly increased at the ipsilesional SVZ of the WT-Vehicle mice in line with the findings of previous studies." (PMID 31606043, 2019). "In the SVZ and peri-infarct regions, cells that were positive for doublecortin (DCX), nestin, and polysialylated neural cell adhesion molecules (PSA-NCAMs) were accumulated in stroke patients." (PMID 29895784, 2018). "We therefore quantified Ki67/GFAP+ cells and DCX+ cells separately along the lateral ventricle in both the ipsilateral and contralateral SVZ 7 days post-stroke at the same anatomical level for all sections (+1.2 mm relative to bregma)." (PMID 24809543, 2014). "These DCX+ cells, did not stain with either Ki67 or GFAP and a significant correlation was also found between infarct volume and the number of DCX positive cells within the SVZ (r = 0.77, P<0.001, n = 15) 7 days post-stroke." (PMID 24809543, 2014). "The number of DCX+ cells was also increased within and surrounding the SVZ 7 days post-stroke compared to sham-operated animals (P<0.05, Scatter plots, Mann Whitney test)." (PMID 24809543, 2014). "In previous studies with this stroke model, we have shown that newborn cells that express doublecortin (DCX) and incorporate BrdU migrate from the SVZ to the stroke region and form new neurons." (PMID 23928330, 2013). "Immunohistochemical analyses of DCX and CD34 in the peri-infarct area of ischemic brain revealed larger number (F5,114 = 212.6, ****P < .0001) of CD34 marker in transplantation cell group of stroke animals compared to vehicle-treated groups." (PMID 38016184, 2024). "Moreover, it notably amplified neurogenic responses post-stroke, evidenced by the proliferation of BrdU/SOX2 and BrdU/DCX in the subventricular zone, and their subsequent differentiation into BrdU/NeuN and BrdU/VgulT1 in the ischemic penumbra." (PMID 39697542, 2024). "For this purpose, we assessed neurogenesis rate by immunolabeling DCX, a marker of NPCs, 1 week after stroke, and found that PDGF-D did not affect DCX+ cell density in the SVZ/LV (VEH:11739 ± 4435, P250:20556 ± 10,095)." (PMID 38769116, 2024). "We found that the standard housing but not the EE increased proliferation of the DCX+ precursors after stroke in the dentate gyrus." (PMID 36831319, 2023). "The same study showed that NICD negative striatal astrocytes generated DCX/Ascl1 neuroblasts from 2 to 7 weeks after stroke, suggesting that Rbpj deletion alone was sufficient to activate their neurogenic program." (PMID 34222228, 2021).
Stroke (continued). "Notably, a study of focal ischemia, a well-characterized stroke model, further enhanced the ability of Neurog2 to drive glial conversion to mature DCX-/NEUN+ iNs compared to the immature DCX+ iNs that predominated in the uninjured brain." (PMID 34291049, 2021). "After ischemic stroke, both groups showed an increase of DCX+ cells in the peri-infarct region, although the stroke response in the irradiation-treated group (IR + IS) was not as pronounced as in the non-irradiated animals." (PMID 32703986, 2020). "When rats subjected to photothrombotic stroke received a single injection of 500 μg OPN into the lateral ventricle of the brain, OPN-treated animals displayed significantly more DCX-positive neuroblasts in the SVZ compared to the placebo-treated controls (p < 0.01)." (PMID 25998490, 2015). "To compare the induction and migration of DCX+ neuroblasts in a striatal stroke, we also carried out proximal MCAo in nestin-Cre ERT2/R26R-YFP animals and compared DCX staining to that in the cortical stroke brain." (PMID 25927436, 2015). "However, at post stroke days 30, there are only very few visible YFP+ or DCX+ cells in the cortical ischemic region (number of DCX+ cells in the cortical ischemic area = 4.84±1.58/section)." (PMID 25927436, 2015). "We reported previously that ablation of doublecortin (DCX)-immunopositive newborn neurons in mice worsens anatomical and functional outcome measured 1 day after experimental stroke, but whether this effect persists is unknown." (PMID 22723908, 2012). "Optogenetic stimulation of GFAP-Arch mice led to not only a reduction in glial scar stiffness but also the increases of EdU+DCX+ and EdU+CD31+ cells, which indicated an increased capacity to promote endogenous neuro-regeneration and angiogenesis for neurological recovery after stroke." (PMID 41346705, 2026). "Anti-IL-6 significantly decreased the number of BrdU+/DCX+ cells in the ischemic SVZ (99 ± 6 vs. 70 ± 7, P < 0.01) and striatum (68 ± 9 vs. 31 ± 5, P < 0.01) of hyperforin-treated mice at 28 dpi, indicating that hyperforin promotes post-stroke neurogenesis via IL-6." (PMID 31133816, 2019). "Since BrdU was administered for the first 14 days after stroke, we concluded that at 2 months post-stroke DCX+ cells with BrdU nuclei did not survive strongly suggesting that the early neuronal progenitors did not survive in the hostile environment of the post-stroke aged brain." (PMID 25002846, 2014). "DCX positive neuroblasts were not however evident within penumbral regions, possibly suggesting a low survival rate of these new neurons with greater stroke severity." (PMID 24809543, 2014). "This assumption is based on our observation of the strong expression of caspase-3 in several EGFP+/DCX+ cells, and their inability to survive in the damaged ischemic region was also described previously in the newly-derived SVZ neuroblasts migrating into the site of injury after stroke." (PMID 22590616, 2012). "Interestingly, under pathological conditions in rodent models of cerebral ischemia or stroke, WBV has been observed to stimulate the expression of several mediators involved in neurogenesis, including BDNF, insulin-like growth factor (IGF-1) and doublecortin (DCX)." (PMID 36412761, 2022). "Under pathological conditions in rodent models like after cerebral ischemia and stroke, WBV may also promote the expression of different neurotrophic factors and neurogenesis-related markers such as brain-derived neurotrophic factor (BDNF), insulin-like growth factor (IGF1), and doublecortin (DCX)." (PMID 35126091, 2021). "We performed permanent photothrombotic stroke in 24-month-old mice followed by DV treatment at 6 h, previously shown to be neuroprotective and promote functional recovery to PSD 7 when DCX is maximally expressed in this model (data not shown)." (PMID 32253702, 2021).
Stroke (continued). "The gliogenic response is however predominant as the SVZ output 2 weeks after stroke comprised 59% GFAP-positive astrocytes, 15–20% OPCs and only 10% DCX-positive neuroblasts, a distribution that almost did not change in the following weeks." (PMID 32982671, 2020). "However, the DCX+ cell density in the ECM was significantly less for 14- (4× less, p < 0.05), but not 28- or 90-days post-stroke conditions." (PMID 34768800, 2021). "At this time, DCX+/BrdU+ cells could be observed in the white matter area between ipsilateral SVZ and ischemic cortex, while these cells were not detectable in non-stroke controls (data not shown)." (PMID 24503654, 2014).
Lissencephaly (70 papers, 2006 to 2026). A spectrum of malformations of cortical development caused by insufficient neuronal migration that subsumes the terms agyria, pachygyria and subcortical band heterotopia. "In hemizygous males, DCX pathogenic variants are usually responsible for lissencephaly and present with agyria or pachygyria with global developmental delay, severe ID, and seizures." (PMID 38612920, 2024). "A wide range of DCX mutation types have been identified in lissencephaly and SBH, including missense, nonsense, frameshift with insertion or deletion, splice site and deletion of exons." (PMID 38612920, 2024). "Pathogenic variants of the DCX gene are the major causes of the “lissencephaly (LIS) spectrum”, which comprehends a milder phenotype like Subcortical Band Heterotopia (SBH) in heterozygous female subjects." (PMID 38791543, 2024). "Since DCX is carried on the X chromosome of males, DCX mutations generally cause classic lissencephaly in males, whereas females have SBH." (PMID 39081427, 2024). "These novel DCX variants further expand the genotypic–phenotypic correlations of lissencephaly spectrum disorders." (PMID 38791543, 2024). "Mutations in the DCX human gene predominantly cause lissencephaly in hemizygous males and subcortical band heterotopia, the ectopic positioning of neurons during cortex development with the formation of ectopic nodules, in heterozygous females." (PMID 36769099, 2023). "Mutations in the LIS1 (lissencephaly-1) or DCX (doublecortin) genes are known to cause lissencephaly." (PMID 38025664, 2023). "While mutations in LIS1 and DCX are associated with the disorder, the exact mechanisms by which they cause lissencephaly are not fully understood." (PMID 38025664, 2023). "Mutations in the DCX gene, which encodes the microtubule-associated protein doublecortin, also cause lissencephaly, however, these mutations are much less common." (PMID 35159273, 2022). "One of the characteristics of DCX-linked lissencephaly is a profound defect in cortical neuronal migration." (PMID 36476638, 2022). "For example, doublecortin mutations are associated with lissencephaly, a disorder of severe cortical malformation." (PMID 38596701, 2022). "Male and female differences have been noted in lissencephaly and SBH related to DCX mutations which predominantly causes lissencephaly in hemizygous males and SBH in heterozygous females." (PMID 35590332, 2022). "For instance, predominantly intrinsic mechanisms underlie lissencephaly caused by mutations in LIS1 (PAFAH1B1) or DCX." (PMID 35733184, 2022). "These mutations, located in the R1 and R2 region of DCX, respectively, cause lissencephaly in humans and have been shown to decrease the cooperative MT binding of DCX." (PMID 36476638, 2022). "DCX is expressed in migrating and differentiating neurons and its mutation is associated with the X-linked lissencephaly." (PMID 36313423, 2022). "Genetic causes of Lissencephaly also involve the DCX gene which is essential for proper neuronal migration." (PMID 36340790, 2022). "Induced pluripotent stem cell-derived neuronal cells from lissencephaly patients with doublecortin mutations display stunted neurite formation." (PMID 38596701, 2022). "In males with DCX deficiency neurons lack completely the protein, giving rise to the more severe lissencephalic “smooth” cortex (Section “Lissencephaly”)." (PMID 36340790, 2022). "The cohort also included one (2.3%; ID 15) patient with lissencephaly caused by a heterozygous splice site variant in DCX." (PMID 34469436, 2021). "The DCX gene is located on the X chromosome, and DCX mutations cause classic lissencephaly (agyria) in males and subcortical band heterotopia (also called double cortex syndrome) primarily in females as a result of neuronal migration defects." (PMID 33199366, 2021).
Lissencephaly (continued). "X-linked lissencephaly results from mutations in X chromosome-residing genes—the Aristaless-related homeobox gene (ARX), and doublecortin (DCX)—which are the two most notable X-linked genes causing lissencephaly." (PMID 35053800, 2021). "Our results indicate that the severity and spatial distribution of agyria in patients with lissencephaly tend to be linked with identified genetic abnormalities (LIS1 or DCX mutation)." (PMID 31355197, 2019). "DCX is an X-linked gene and mutations in men result in complete lissencephaly while in females, the mutation is associated with ectopic neuronal layering, such as in subcortical band heterotopia or double cortex." (PMID 32038172, 2019). "Involvement of cerebellum in lissencephaly has been associated with the mutations of DCX, TUBA1A, and LIS1 genes, and represents a distinctive heterogeneous group of cortical malformations." (PMID 31355197, 2019). "Although LIS1 variants have been associated with isolated lissencephaly, where the parietooccipital brain region is more affected, DCX variants often give rise to malformations of the frontal cortex." (PMID 31231230, 2019). "Variations of PAFAH1B1 are linked to a posterior-to-anterior gradient of lissencephaly, while mutations of DCX are associated with an anterior-to-posterior gradient." (PMID 29628935, 2018). "Newly generated cells migrating from the neurogenic zones are DCX positive, and mutations in the DCX protein would lead to migration disorders causing lissencephaly and SBH." (PMID 28701917, 2017). "Mutations in LIS1, located on chromosome 17p13.3, or DCX on Xq23 are the main cause for classical lissencephaly." (PMID 26052266, 2015). "Mutations in lissencephaly 1 (LIS1) and doublecortin (DCX) have been shown to cause type I lissencephaly." (PMID 26541977, 2015). "Females with a mutation affecting one copy of the DCX gene usually develop subcortical band heterotopia while males with one DCX gene mutation show isolated lissencephaly." (PMID 26541977, 2015). "More importantly, DCX is associated with the neuronal migration disorders, lissencephaly, pachygyria, and subcortical band heterotopia." (PMID 26541977, 2015). "Classical lissencephaly caused by LIS1 or DCX mutations usually exist in isolated forms and only show cortical dysplasia on brain MRI." (PMID 26052266, 2015). "Missense mutations in DCX responsible for lissencephaly spectrum are mainly located in two tandem repeats (N-terminal or C-terminal doublecortin domains), which bind to microtubules or free tubulin and other components, respectively." (PMID 26052266, 2015). "Abnormal microtubule functions dependent on DCX appear to underlie lissencephaly because pathological mutations in DCX prevent its product binding and subsequent stabilization of microtubules." (PMID 26541977, 2015). "Classic lissencephaly (type I) includes isolated lissencephaly and subcortical band heterotopia (“double cortex”) which are caused by DCX mutations." (PMID 26541977, 2015). "Mutations in LIS1 and DCX account for approximately 85% of patients with the classic form of lissencephaly." (PMID 26541977, 2015). "Lissencephaly can be associated with congenital microcephaly, though the head circumference of lissencephaly caused by the LIS1 or DCX mutations is usually within the normal range." (PMID 26052266, 2015). "Mutations in DCX are causative for classical lissencephaly in male individuals and subcortical band heterotopia in female individuals." (PMID 26052266, 2015). "In contrast to lissencephaly caused by mutations in DCX, LIS1 mutations preferentially affect the parieto-occipital cortex." (PMID 26541977, 2015). "The X-linked dysgenesis that manifests as lissencephaly in males and subcortical heterotopia in females has been shown to be due to mutations in the doublecortin gene that is highly expressed in fetal brain." (PMID 24950657, 2014).